CGAS (cyclic GMP-AMP synthase)
Diseases named in the same sentence as CGAS in open-access papers (continued):
Sharing a sentence is not in itself a finding about the gene and the disease.
tumor (continued). "In turn, these events lead to a tumor cell-intrinsic cytosolic DNA response involving cGAS-STING-dependent activation of downstream NC-NF-κB signaling, which promotes tumor metastasis and tumor immunosuppression." (PMID 38167338, 2024). "The cyclic GMP-AMP synthase (cGAS) / STING pathway is integral to the innate response in tumor immunity 24, 25, contributing significantly to dendritic cell maturation and facilitating cytotoxic T cell infiltration and activation." (PMID 39346548, 2024). "Another way to activate cGAS is through dying tumor cells, which release DNA into their surroundings." (PMID 38660307, 2024). "In this regard, the inherent detection mechanisms of tumors and innate immune cells, notably involving cGAS/STING—a cytosolic DNA sensor—have demonstrated utility in increasing anti-tumor response." (PMID 38785789, 2024). "The cGAS-STING pathway as an innate immune sensor plays a crucial role in triggering anti-tumor immunity." (PMID 38592428, 2024). "In this work, we provide evidence that stimulating TET2 activity by VC combined with VC-induced dsDNA leakage activate tumor cGAS-cGAMP-endothelial STING pathway and promote lymphocyte trafficking." (PMID 38177099, 2024). "Here, we show that OGT is essential for tumor growth in immunocompetent mice by repressing the cyclic GMP-AMP synthase (cGAS)-dependent DNA sensing pathway." (PMID 39365288, 2024). "cGAS is a cytosolic DNA sensor that activates the type I interferon pathway and promotes tumor metastasis in breast cancer." (PMID 39201539, 2024). "The mechanism of action of these chemotherapeutic agents is to induce DNA fragmentation in tumor cells, and these broken DNA molecules activate the cGAS-STING pathway in different ways." (PMID 39464890, 2024). "Specifically, the POLE mutation leads to genomic instability and increased DNA damage, upregulates cytoplasmic DNA, triggers cGAS, and initiates downstream signaling, thereby stimulating the expression of inflammatory genes and anti-tumor immune responses." (PMID 39445027, 2024). "Increasing evidence suggests that the cGAS-STING pathway plays a key role in tumor immunity, and the combination of STING-related agonists can significantly enhance the efficacy of immunotherapy and reduce the emergence of immunotherapeutic resistance." (PMID 39464890, 2024). "Herein, using preclinical liver cancer models in Cgas/Sting-deficient male mice, we report that the interdependence between tumor cGAS and host STING mediates vascular normalization and anti-tumor immune response." (PMID 38177099, 2024). "Activation of the cGAS–STING signaling pathway in the TME can trigger specific monitoring of tumor Ags and promote effector T cells to infiltrate tumor tissue." (PMID 38525112, 2024). "Further investigation of tumor infiltration of immune cells and cGAS/STING knockout studies identified CD8+ T‐cell recruitment via STING pathway activation as a critical determinant of the anti‐tumor immunity efficacy of PARP inhibition and CDC7i in OV." (PMID 39412086, 2024). "Collectively, these findings imply that pharmacological VC not only activates tumor cGAS through cytoplasmic dsDNA leakage, but also increases tumor cGAS expression via epigenetic modifications by Tet2-dependent DNA demethylation." (PMID 38177099, 2024). "We observed a positive correlation between cGAS-STING scores and tumor mutational burden (TMB, r = 0.254, P < 0.001), homologous recombination deficiency (HRD, r = 0.296, P < 0.001) and intratumor heterogeneity in the TCGA cohort (r = 0.28, P < 0.001)." (PMID 38167507, 2024). "The accumulating tumor pathological DNA in the cytoplasm can activate the cGAS-STING signaling pathway, inducing innate immunity and promoting adaptive immunity." (PMID 38347787, 2024). "Recent studies have revealed that DNA damage response inhibitors (DDRI), such as poly ADP-ribose polymerase inhibitors (PARPI), can enhance anti-tumor immunity by activating the cGAS-STING pathway." (PMID 38566036, 2024).
tumor (continued). "In summary, our results identify OGT-mediated genomic stability and activate cGAS-STING pathway as an important tumor cell-intrinsic mechanism to repress antitumor immunity." (PMID 38168435, 2024). "Metal ions, especially manganese ions (Mn2+), play a significant role in anti-tumor immunity by activating the cyclic GMP-AMP synthase stimulator of the interferon gene (cGAS-STING) signaling pathway." (PMID 38675217, 2024). "Overall, cGAS/STING activation appears to be relevant for enhancing anti-tumor immunity in the context of HRD cancers both at baseline and upon DNA-damaging therapies." (PMID 39544936, 2024). "Understanding the balancing act between pro- and anti-tumor inflammatory signaling upon cGAS/STING activation is likely to point the way forward in therapeutic manipulation of this pathway." (PMID 39544936, 2024). "Conversely, recent work has shown that chronic activation of cGAS/STING favors tumor growth, specifically in the context of cancers displaying high levels of CIN." (PMID 39544936, 2024). "APC uptake of tumor DNA activates the cGAS–STING signal and induces the production of IFN‐I and cytokines (such as IL‐12), as well as the expression of costimulatory molecules (such as CD40, CD80, and CD86)." (PMID 38525112, 2024). "Taken together, these results indicated that RSK2-mediated cGAS phosphorylation at Ser120 and Thr130 by tumor promoter stimulation increases cGAS chromatin incorporation." (PMID 39424777, 2024). "A crucial requirement for clinical applications is to explore NK cell activation approaches in a tumor‐derived cGAMP‐independent manner through activating NK cell intrinsic cGAS." (PMID 39206412, 2024). "Correlation between the native immune response and the expression of antigen-presenting genes of each tumour subtype indicates that only the expression of YAP1 positively correlates to cGAS, STING, HLA-E and other interferon-inducible genes." (PMID 39215193, 2024). "This evidence indicates that the intrinsic anti-tumor effects of the cGAS-STING pathway in tumors are based on its normal physiological functions, like inducing apoptosis, releasing pro-inflammatory, and transferring cGAMP." (PMID 38523155, 2024). "Mechanistically, tumor cGAS produces cGAMP, which further transports via LRRC8C channels to activate STING in endothelial cells, enhancing recruitment and transendothelial migration of lymphocytes." (PMID 38177099, 2024). "The cGAS-STING pathway and its downstream effects mediate the polarization of tumor-associated macrophages." (PMID 39464890, 2024). "Together, these results suggest that tumor cGAS controls vascular normalization and anti-tumor immune response in an intrinsic STING-independent manner." (PMID 38177099, 2024). "In response to the tumor-suppressor function of cGAS-STING, cancer cells tend to downregulate these proteins." (PMID 39445027, 2024). "While in some tumor cells, enriched cGAS/STING signaling kindles a tumor-promoting function by activating NF-κB, TBK1, and IRF3." (PMID 38474405, 2024). "Perhaps more importantly, our studies suggest that activation of tumor cell intrinsic cGAS/STING signaling is likely to be a double-edged sword." (PMID 39469633, 2024). "The sensing of this cytosolic dsDNA by cGAS leads to cGAMP production, which can have several different fates ultimately leading to the production of type I interferon in the tumor." (PMID 38659582, 2024). "Mechanistically, RTRT induced catastrophic dsDNA in tumor cells, which activated the cGAS-STING pathway." (PMID 39736508, 2024). "Tumor-derived exosomes activate the cGAS-STING pathway in naive lymphocytes, activating Foxp3, STAT5, and SMAD3 to promote the transformation of naive CD4+ T cells into Treg cells, thereby mediating immunosuppression." (PMID 39464890, 2024). "cGAS/STING signalling appears to drive an innate immune response against tumours and potentiates the efficacy of other common therapies including chemo and radiotherapy." (PMID 39403376, 2024).
tumor (continued). "The relieved tumor hypoxia improved the radio-sensitivity of tumor, amplifying RT-caused ICD and cGAS-STING activation." (PMID 38831378, 2024). "The activation of cGAS-STING signaling in tumor cells drives IFN production as a process of cGAS-STING signaling and SLC14A1 CAF differentiation." (PMID 38659423, 2024). "NK cell–intrinsic STING interacts with tumor cell‐inherent cGAS via cGAMP transport to enhance the antitumor response of NK cells." (PMID 39206412, 2024). "Here, the authors show that targeting PRMT3 markedly improves the anticancer efficacy of ICB via interrupting HSP60 methylation and oligomerization, damaging mitochondrial integrity, and thereby activating cGAS/STING-mediated anti-tumor immunity." (PMID 39256398, 2024). "Overexpressing cGAS-S37D rescued tumour formation and growth in knockdowns, whereas cGAS-S37A did not." (PMID 39080411, 2024). "Together, these results indicate that tumor cGAS-mediated tumor repression, vascular normalization, and anti-tumor immune response rely on host STING." (PMID 38177099, 2024). "cGAS is integral in several cellular responses to DNA damage, which can lead to the onset and progression of GI cancers or, alternatively, anti-tumor immunity." (PMID 39050748, 2024). "The impact of the cGAS-STING pathway on tumor metastasis is one of the most contentious topics in this area." (PMID 38523155, 2024). "Activation of cGAS-STING signaling was reported to promote tumor metastasis, which, however, is distinct from its roles in regulating adhesion and migration in macrophages." (PMID 39304793, 2024). "Some groups find that only the production of cGAS, but not the STING response, by the tumor cells is important; tumor-produced extracellular cGAS activates STING in immune cells in the tumor microenvironment." (PMID 38358346, 2024). "Irradiation of 50% of tumor cells induced similar levels of DAMPs release, DNA damage, and cGAS-STING pathway activation as observed with 40% irradiation, with a higher trend." (PMID 39736508, 2024). "A deeper comprehension of the interplay between m5C methylation and TLRs, cGAS-STING, and RLRs offers novel insights into mechanisms underlying the anti-tumor actions of the immune system." (PMID 38807595, 2024). "This prompts heightened sensitivity of cGAS to mtDNA, thereby further amplifying the potent anti-tumour immunity stemming from STING pathway activation." (PMID 38816831, 2024). "On the other hand, extensive observations suggest that chronic activation of the cGAS/STING pathway can induce an immune suppression in the tumor microenvironment that promotes the progression of the tumor." (PMID 38474014, 2024). "In tumor treatment, especially RT, the unique inhibitory regulatory pattern of cGAS/STING signaling in tumor cells remains to be further elucidated." (PMID 39621310, 2024). "Overexpression of NF-κB p65 and silenced expression of cGAS are often critical triggers contributing to tumor initiation, drug resistance, and treatment evasion." (PMID 38782895, 2024). "PP6 responses to innate immune signals via the cGAS-STING pathway, and is implicated in tumor suppression due to its role in restricting cell cycle progression." (PMID 38965614, 2024). "Consistent with previous tumour growth observation, cGAS-knockdown tumours grew slower than controls under saline treatment." (PMID 39080411, 2024). "In the process of cell carcinogenesis, type I IFN produced by activation of the cGAS-STING pathway provides a key signal for anti-tumor immunity." (PMID 38495488, 2024). "In esophageal squamous cell carcinoma, irradiation of tumor cells can activate the cGAS-STING pathway and promote IL-34 secretion, thereby promoting the polarization and recruitment of M2 macrophages and tumor cell survival." (PMID 39464890, 2024).
tumor (continued). "The essence of the killing effect of radiotherapy is the DNA damage of tumor cells, and the cGAS–STING pathway mediates antitumor immunity through sensing cytoplasmic DNA, contributing to radiotherapeutic responses." (PMID 38379323, 2024). "To clarify the role of the cGAS-STING-NF-κB/IFNβ signaling pathway in the anti-tumor response to zebularine, we treated Cgas-/-, Sting-/-, and sh-Rela/p65 B16F10 tumors implanted into wild-type mice, and sh-Ifnar1 B16F10 tumors implanted into IFNAR1-/- mice." (PMID 38755254, 2024). "Altogether, these data underscore the importance of the cGAS/STING-driven inflammatory phenotype in MMRd tumors for optimal anti-tumor immunity." (PMID 39544936, 2024). "The application of immune checkpoint inhibitors can relieve the inhibition of the immune response by the tumor and enable the immune response induced by the cGAS-STING pathway." (PMID 39445027, 2024). "Phagocytosis of extracellular tumor DNA by DCs triggers the activation of the cGAS-STING-IFN pathway." (PMID 38168435, 2024). "6TdG treatment in vivo led to activation of the CD8 T cells and NK cells against tumor cells dependent on tumor cGAS/ STING signaling." (PMID 38253555, 2024). "Accordingly, cGAS and STING deficiency in MC38 tumor cells resulted in the loss of type I IFNs induction upon Mn‐N/C plus H2O2 treatment." (PMID 38308189, 2024). "In tumours, as a response to DNA fragments, IFNα and IFNβ are secreted by cancer cells and DCs, resulting in the activation of the cGAS/STING pathway with the consequent T cell priming and anti-tumour activity." (PMID 38339377, 2024). "Commonly, research involves the deletion of the cGAS-STING pathway in specific subtypes of cells before or at the early stages of tumor formation, with scant exploration of its functions in the middle or later stages of tumors." (PMID 38523155, 2024). "The cancer-intrinsic cGAS/STING signaling pathway plays a critical role in tumor suppression and immune surveillance through the activity of the IFN-I pathway." (PMID 38564022, 2024). "An important part of the tumor immune microenvironment is shaped by the cGAS–STING signaling pathway." (PMID 39290276, 2024). "Our findings uncover the role of tumor suppressor TET2 in anti-tumor immunity via cGAS-STING-mediated vascular normalization." (PMID 38177099, 2024). "Multiple studies have helped clarify the role of the cGAS-STING pathway in the tumor microenvironment." (PMID 38659582, 2024). "The CCRT we used is known to enhance tumor immunogenicity by releasing tumor antigens through immunogenic cell death and activating innate immunity pathways such as the cGAS-STING pathway." (PMID 39763661, 2024). "This difference can be attributed to the fragility and proneness to leakage of tumor cell DNA during tumoral progression, thereby precipitating the activation of the cGAS-STING signaling pathway." (PMID 39170700, 2024). "By priming T cell responses and increasing tumor immunogenicity, the cGAS-STING axis promotes tumor rejection." (PMID 39043779, 2024). "In summary, anti-tumor immune responses can be effectively enhanced by targeting the cGAS-STING signaling pathway." (PMID 39867908, 2024). "Yet, loss of function mutations in either cGAS or STING account for less than 1% of all cancer types, potentially explained by the tumor-promoting role of this pathway." (PMID 39544936, 2024). "Here, we show that OGT is essential for tumor growth in immunocompetent hosts by repressing the cyclic GMP-AMP synthase (cGAS)-dependent DNA sensing pathway." (PMID 38168435, 2024). "This certainly suggests that tumor‐derived exosomes play different roles in 2′3′‐cGAMP or LL‐37‐2′3′‐cGAMP induced cGAS‐STING signaling." (PMID 38498770, 2024). "In contrast, acute activation of the cGAS-STING pathway often leads to anti-tumor immunity through TBK1-dependent activation of IRF3 and canonical NF-κB p65/p50 signaling, which mediate the transcription of type I IFN signaling." (PMID 38167338, 2024).
tumor (continued). "There was clearly variability in the extent of pSTING, as the activation of the cGAS/STING pathway will depend largely on the apoptotic drivers experienced in each tumor, which will depend on various parameters like the TME and hypoxic conditions." (PMID 39199688, 2024). "Given these complexities, targeting the cGAS-STING pathway in cancer therapy involves carefully modulating its activity to enhance anti-tumor immunity while minimizing potential pro-tumorigenic effects." (PMID 40018367, 2024). "Recent research has demonstrated that the radiation treatment and the consequent anti-tumor efficacy are closely connected to the activation of the cGAS-STING pathway and the production of IFN." (PMID 38347787, 2024). "Collectively, all results verified that tumor exosomal ENPP1 plays an important role in the hydrolysis 2′3′‐cGAMP bound to LL‐37 to inhibit cGAS‐STING signaling." (PMID 38498770, 2024). "By understanding and subsequently blocking pro-tumoral pathways, it is possible to ensure that the cGAS-STING pathway in T cells is steered towards anti-tumor activity." (PMID 38523155, 2024). "This cGAS–STING signaling‐pathway‐mediated tumor cell suppression is thought to be mediated through the regulation of type I IFN (IFN‐α and IFN‐β) and other proinflammatory genes." (PMID 37560754, 2023). "Our findings reveal that 56.8% of all pMMR CRC cases were cGAS-negative/STING-negative expressions (cGAS−/STING−) in tumor cells, whereas only 9.9% of all pMMR CRC showed cGAS-positive/STING-positive expression (cGAS+/STING+) in tumor cells." (PMID 37345163, 2023). "Integrating AIEgen-based phototherapy and gas-mediated immunostimulation strategy of cGAS-STING pathway activation into the virus-inspired gas nanoadjuvant illustrates a paradigm for photoimmunotherapy of poorly immunogenic tumor." (PMID 37221157, 2023). "Mechanistically, Aurora A directly bound to and phosphorylated cyclic GMP-AMP synthase (cGAS), suppressing PD-L1 expression in tumor cells." (PMID 36928177, 2023). "Evidence suggests that cGAS–STING signaling‐pathway‐mediated autophagic tumor cell death occurs through the formation of micronuclei upon sensing aberrant cell fusion." (PMID 37560754, 2023). "Further understanding the interaction of cGAS-STING signaling, gut bacteria and the tumor microenvironment is critical to evaluate the possibility of targeting the cGAS-STING pathway in clinical implications." (PMID 37781354, 2023). "The activity of cGAS is often diminished in tumor cells due to epigenetic modifications, a process mitigated by DNA methylation inhibitors." (PMID 37920470, 2023). "In pancreatic cancer cGAS-STING-induced regulatory B-cells compromise NK cells anti-tumor immune response." (PMID 37854446, 2023). "In disease environments that require high levels of cGAS activation, such as tumor environments, this function of Mn2+ has great potential in the immunotherapy of diseases." (PMID 37153576, 2023). "In tumors, DNA or cGAMP from dying tumor cells access the cytosol of APCs and activate the cGAS–STING pathway, leading to the induction of type I IFNs and other immune stimulatory molecules, which are essential in modulating the functions of immune cells." (PMID 37560754, 2023). "Together, these results demonstrated that the Arf1‐ablated tumor cells induced the activation of the cGAS‐STING signaling pathway in DCs both in vitro and in vivo." (PMID 37786300, 2023). "Recent studies have elucidated the intricate interplay between PARP inhibitors and the innate immune response in tumor cells, particularly through the cGAS-STING pathway." (PMID 38111536, 2023). "Modulators of the cGAS-STING pathway were first developed for tumor therapy, and STING agonists have been used in combination with other drugs to inhibit tumor growth." (PMID 37600809, 2023).